PPIB (peptidylprolyl isomerase B)
Diseases named in the same sentence as PPIB in open-access papers (continued):
Sharing a sentence is not in itself a finding about the gene and the disease.
tumor (118 papers, 2007 to 2026). "Our results showed that AML and CML differ in the expression of GBF1, CD177, OLFM4 and peptidylprolyl isomerase B (PPIB) implicated in the intercellular interactions and chemotaxis regulation to regulate tumor cell migration and invasion." (PMID 36230605, 2022). "PPIB, also named cyclophilin B, has been implicated in chemoresistance and radioresistance of tumors, but is largely undiscovered in tumor metastasis." (PMID 35379924, 2022). "Our results demonstrate that extracellular PPIB also functions as a novel antitumor protein, exhibiting tumor-killing capacity in a dose-dependent manner." (PMID 38360722, 2024). "In parallel, wound‐healing assays showed a significant decrease in the migration ability of tumour cells with the downregulation of PPIB expression levels." (PMID 39031800, 2024). "In PPIB-injected mice subcutaneous tumor tissues, the elevated ratio of TUNEL-positive cells was witnessed, and increased expressions of GDF15 were probed." (PMID 38360722, 2024). "Antitumor protein PPIB has been identified by us to play an antitumor role in bystander effect; thus, we investigated if PPIB can independently kill tumor cells by promoting ERS-induced apoptosis." (PMID 38360722, 2024). "PPIB catalyzes the cis-trans isomerization of peptide bonds, but little is known about its tumor-suppressive mechanism." (PMID 36943734, 2023). "Specifically, in the tumour region, we observed enrichment of PPIB and UGT2B15 and IFI27, NDRG1, BHLHE40 and VEGFA." (PMID 35109839, 2022). "Differential expression analysis of the hyperexpanded clones compared to all other clones revealed an elevated expression of tumor promoting factors/oncogenes (HSPA5, PDIA4, MANF, PPIB) and a gene associated with malignant B cell clones (CD63)." (PMID 36153593, 2022). "PPIB, UGT2B15 and IFI27, which were found in tumour cluster A, were mainly associated with cell survival and apoptosis." (PMID 35109839, 2022). "Cox proportional regression model was used to identify a four-gene (WIPF1, PPIB, BASP1, PLOD2) signature that were significantly associated with overall survival (OS), and all the four genes were significantly upregulated in tumor tissues." (PMID 34257533, 2021). "Two-hundred-and-thirteen tumours had positive PPIB mRNA signals with 141/213 tumours being scored 2 or greater for PPIB staining." (PMID 34287743, 2021). "Base Scope assay was performed to observe the subcellular localization of lnc-HSD17B11-1:1 with PPIB control in CRC tumor tissues and adjacent normal tissues." (PMID 32595704, 2020). "Furthermore, plate cloning assays revealed a marked decrease in tumour cell abundance upon PPIB knockdown, signifying a dampened proliferative and invasive propensity compared with control conditions." (PMID 39031800, 2024). "Furthermore, the intratumoral injection of PPIB recombinant protein led to the repression of MDA-MB-231 subcutaneous xenograft tumor growth in nude mice." (PMID 38360722, 2024). "In addition, PPIB may interact with other immunomodulatory factors in the tumour microenvironment to influence T‐cell infiltration and activity." (PMID 39031800, 2024). "The unique interplay of proteins like PCOLCE, H4, PPIB, and ALDOA within LIV-treated MSC CM underscores their tumor-suppressive attributes." (PMID 38389836, 2024). "Proteomics analysis revealed that heat shock protein 90 (Hsp90ab1), calreticulin (Calr) and peptidylprolyl isomerase B (Ppib), which are highly expressed intracellular proteins in many cancers, were enriched in MSC CM as atypical tumor suppressors." (PMID 33859739, 2021). "Three positive control probes, POLR2A, PPIB and UBC were applied to FFPE sections from a range of tumour types in FFPE whole-face (prospective collection) or TMA (retrospective collection) formats and evaluated semi-quantitatively and by image analysis." (PMID 29212158, 2017).
tumor (continued). "Quantification of POLR2A, PPIB and UBC was performed using Spotstudio software in 6 distinct regions of interest (ROI), 3 from tumour and 3 from stromal compartment of each tissue block." (PMID 29212158, 2017). "On initial microscopic evaluation the 4 tumour types showed uniform expression levels of the RNAscope control probes POLR2A, PPIB and UBC across the entire surface area of all tissue sections." (PMID 29212158, 2017). "This was evidenced by smaller tumor volumes and lighter tumor weights, as well as decreased expressions of Ki-67 and PCNA, demonstrating the in vivo antitumor effect of PPIB." (PMID 38360722, 2024). "Of the remaining 41 genes, three (PIGC, PKM and PPIB) were commonly upregulated with oncogenic potential and 31 were commonly downregulated among CP and PDAC-CP, of which, 3 (AZGP1, EGLN1 and GNMT) were tumour suppressors." (PMID 35854233, 2022). "All tumor resections had adequate RNA integrity and acceptable background as determined by presence of PPIB signal and absence of dapB signal, respectively." (PMID 33972574, 2021). "For some tumor resections, less intense DKK1 and PPIB signal was observed." (PMID 33972574, 2021). "Together with the tumor-suppressing proteins such as CALR, ENO1, HSP, MSN, and UBC, which were enriched in tumor-suppressive CM, six recombinant proteins, such as HISTONE H4, PPIB, GJA1, CPE, S100A11, and PCOLCE, were identified as extracellular tumor-suppressing proteins." (PMID 36943734, 2023).
cancer (100 papers, 2010 to 2025). A tumor composed of atypical neoplastic, often pleomorphic cells that invade other tissues. "The genes BLK, CDC247, CSK, IRF5, STAT1, STAT4, and TNIP1 are associated with AIDs, and CDC37, DDX6, HSPA6, MAPT, PPIB, STAT1, and STAT4 are associated with cancers." (PMID 40429780, 2025). "The PPIB nuclear to cytoplasm ratio remained unchanged at 47.7% and 46.7% in benign to low-grade and high-grade cancer, respectively (p = 0.8381)." (PMID 36674564, 2023). "Another study evaluated the expression of 41 genes as a function of in vitro radioresistance in the NCI-60 cancer cell line panel and found that PPIB had the strongest direct correlation." (PMID 36983764, 2023). "Inhibition of PPIB expression by siRNA increased the radiosensitivity of cancer cells and inhibited DNA repair." (PMID 31040200, 2019). "The PPIB positive signal on xenograft HeLa cell and human cancer tissues simultaneously validated the procedure." (PMID 30189670, 2018). "In our study, LUSC patients with high expression of PPIB acquired survival benefits, suggesting that the functions of PPIB may be diverse in different types of cancer." (PMID 37280525, 2023). "In contrast to ANO7, PPIB expression gradually increased from benign to high-grade cancer." (PMID 36674564, 2023). "Immunohistochemical analysis showed cytoplasmic expression of PPIB in carcinoma cells." (PMID 24339976, 2013). "However, the exact molecular mechanism by which PPIB leads to cancer cell survival is unclear." (PMID 34257533, 2021). "PPIB mRNA ISH signal was prominent in all three cases and stained both cancer and stromal cells, and the dapB probe resulted in no ISH signal, with only some un-specific chromogen depositions in focal areas." (PMID 30999696, 2019).
infection (86 papers, 2005 to 2026). The state of being infected such as from the introduction of a foreign agent such as serum, vaccine, antigenic substance or organism. "A follow-up study demonstrated that PpiB contributes to virulence in a murine abscess model of infection, independently of its PPIase activity." (PMID 31208155, 2019). "Previously, we identified two PPIase enzymes in Staphylococcus aureus (PpiB and PrsA) that are involved in the regulation of virulence determinants and have shown that PpiB contributes to S. aureus virulence in a murine abscess model of infection." (PMID 31208155, 2019). "Due to the contribution of these two PPIases to the regulation of multiple virulence determinants, we hypothesized that PrsA and PpiB would contribute to virulence in a murine systemic model of infection using a community acquired methicillin-resistant S. aureus (CA-MRSA) USA300 strain." (PMID 31208155, 2019).
PPIB also shares sentences with these, for which no sentence is quoted: Hepatitis (683 papers); hepatitis B (68); influenza (56); Obesity (16); primary immunodeficiency (15); systemic lupus erythematosus (15); COVID-19 (14); viral infection (12); Hypertension (10); syphilis (10); autoimmune disease (8); malaria (8); pancreatic cancer (8); rheumatoid arthritis (8); colon carcinoma (7); leukemia (7); metabolic syndrome (7); non-small cell lung carcinoma (7); Sjögren’s syndrome (7); acute lymphoblastic leukemia (6); acute myeloid leukemia (6); Autoimmunity (6); chronic hepatitis B (6); chronic lymphocytic leukemia (6); gastric cancer (6); glioblastoma (6); glioma (6); tetanus (6); viral hepatitis (6); Alzheimer disease (5).
A further 292 diseases each share a sentence with PPIB in 5 papers or fewer.